BDNF (brain derived neurotrophic factor)
Diseases named in the same sentence as BDNF in open-access papers (continued):
Sharing a sentence is not in itself a finding about the gene and the disease.
tauopathy (23 papers, 2013 to 2026). Neurodegenerative disorders involving deposition of abnormal tau protein isoforms (tau proteins) in neurons and glial cells in the brain. "We were thus surprised and excited to localise nucleolar tau in retinoic acid and brain-derived neurotrophic factor (BDNF) differentiated SHSY5Y cells —a widely used model for studying cellular changes associated with tauopathy." (PMID 26751496, 2016). "In the present study, we investigated the therapeutic effects of BDNF on tauopathy in a P301L mouse model, using an adeno-associated virus (AAV)-mediated delivery method." (PMID 27701410, 2016). "For example, dysregulated signaling of brain-derived neurotrophic factor (BDNF) is strongly associated with neurodegenerative diseases, but how BDNF signaling affects tauopathy or vice versa remains unclear." (PMID 34445171, 2021). "Finally, in a mouse model of early tauopathy, the retina of human mutated P301S tau mice, the activity-dependent secretion of BDNF is impaired." (PMID 29249935, 2017). "Further studies are required to examine the mechanism of BDNF on tauopathies in humans and animal models." (PMID 35090576, 2022). "A reduction of BDNF brain expression was also observed not only in AD but also in patients with different neurodegenerative disease, and specifically in other tauopathies, such as Pick's disease and corticobasal degeneration." (PMID 29249935, 2017). "Here, we found that the BDNF level was reduced in the serum and brain of AD patients and P301L transgenic mice (a mouse model of tauopathy)." (PMID 27701410, 2016). "In conclusion, the present study uncovered the therapeutic effects of AAV-BDNF on tauopathy, suggesting that BDNF supplement is a promising strategy for prevention and treatment of AD and other neurodegenerative diseases with tauopathies." (PMID 27701410, 2016). "BDNF levels are reduced in serum and brain samples from mouse models of tauopathy." (PMID 35008438, 2021). "In spite of this, given that BDNF polymorphism and reduction are related with AD and other diseases with tauopathies, and the protective effect of BDNF in P301L mice, BDNF treatment might also be beneficial in other neurodegenerative diseases with tauopathies." (PMID 27701410, 2016). "However, the direct therapeutic effect of BDNF supplement on tauopathy in AD remains to be established." (PMID 27701410, 2016). "Furthermore, decreased BDNF mRNA and protein levels are observed in tauopathies and neurodegenerative disease." (PMID 26059363, 2015). "Our data also highlight BDNF signaling as a feasible target for drugs against tauopathies." (PMID 24618580, 2014). "Next, we further determined whether the BDNF reduction was independent of neuron loss, the characteristic of tauopathy." (PMID 27701410, 2016). "FX5 ameliorated synaptic impairment through GR/BDNF/TrkB/CREB pathway, protected against neuronal apoptosis by repressing GR/PI3K/AKT/GSK3β pathway-mediated tauopathy and subsequent ER stress and repressed inflammation through GR/NF-κB/NLRP3/ASC/Caspase-1 pathway." (PMID 35260821, 2022). "In contrast, BDNF-HA expression in zebrafish embryos was not sufficient to suppress tauopathy-elicited neurotoxicity." (PMID 26852117, 2016). "This improvement in axonal transport is independent of any BDNF-mediated neuroprotective increase in cell body or axon number, effects that have been previously reported, as it occurs without RGC loss in naive animals, early after injury and in the P301S tauopathy model of reduced axonal transport." (PMID 33789891, 2021).
neuropathy (22 papers, 2011 to 2025). A disorder affecting the nervous system that manifests with pain, tingling, numbness, and/or muscle weakness. "Higher levels of BDNF have been associated with lower severity CIPN symptoms, while lower levels of BDNF have been associated with higher severity neuropathy." (PMID 35267533, 2022). "For instance, studies have demonstrated that factors such as the brain-derived neurotrophic factor (BDNF) can enhance corneal epithelial health and sensitivity, addressing the underlying neuropathy that characterises the ocular complications in diabetic patients." (PMID 39797325, 2025). "Recent studies have highlighted the utility of biomarkers, such as NGF and BDNF, in predicting the progression of neuropathy and response to therapy." (PMID 40274830, 2025). "Biomarkers like nerve growth factor (NGF), brain-derived neurotrophic factor (BDNF), and oxidative stress markers (e.g., malondialdehyde) are gaining attention for their utility in early neuropathy detection." (PMID 39857603, 2024). "In works studying the role of BDNF in the development of neuropathy, the idea of the involvement of the higher cortex as one of the main fields of influence of this protein was traced." (PMID 37092524, 2023). "To study the contribution of sensory BDNF to the development and maintenance of chronic pain, we used the formalin model of inflammation, a modified Chung and Seltzer models of neuropathy and a model of hyperalgesic priming." (PMID 29394316, 2018). "In contrast, we observed normal development of acute and chronic neuropathic pain in the Seltzer model, indicating differences in the contribution of BDNF to distinct models of neuropathy." (PMID 29394316, 2018). "Neuropathy leads to the activation of spinal glial cells and to the release of brain-derived neurotrophic factor (BDNF), which results in the downregulation of KCC2." (PMID 23602194, 2013). "Neurons expressing BDNF underinflammation/neuropathy or chronic pain are in fuchsia." (PMID 38785946, 2024). "We next sought to identify whether alterations in the BDNF/TrkB pathway correlate with neuropathy in CMT2D." (PMID 36928301, 2023). "In animals treated with BML-111, the BDNF increase induced by neuropathy was reduced." (PMID 35454990, 2022). "Finally, we have revealed that iBAT and scWAT differ in their patterns of innervation and response to neuropathic stimuli, and that male and female mice differ in scWAT innervation with a blunted response to neuropathy and higher levels of BDNF." (PMID 31509546, 2019). "Thus, boosting the availability of specific growth factors such as BDNF in a spatial and time-dependent manner may address the therapeutic needs of one of the most widespread forms of human neuropathy." (PMID 36928301, 2023). "In this research, we furthermore analyzed the impact of DADS and GYY4137 on the p-IKBα, BDNF, CB2R, NRF2 and HO-1 protein levels in the PFC, vHIP and PAG of animals with nerve injury-provoked neuropathy." (PMID 37371911, 2023). "These neuropathy molecules include CGRP(↓), substance P(↓) and BDNF(↑), neuropeptide Y(↑), galanin(↑) via glial activation, which in turn activates the TNFα, MCP-1 and TLR4 pathways." (PMID 21996269, 2011). "The over-expression of P2X4 in Schwann cells have recently been shown to promote remyelination via secretion of brain derived neurotrophic factor, and another P2X receptor P2X7 has been shown to be involved in Charcot-Marie-Tooth disorder, a common inherited human neuropathy with demyelination." (PMID 31379513, 2019). "Moreover, differences in levels of BDNF expression in DRG following distinct rhizotomy and transection models of neuropathy have been reported previously." (PMID 29394316, 2018). "In neuropathy, BDNF, brain derived neurotrophic factor, is a member if nerve growth factor family." (PMID 28761062, 2017).
neuropathy (continued). "An important implication of our findings is that BDNF expressed in sensory neurons is not essential for acute mechanical pain, but is critical for the transition from acute to chronic pain in models of inflammation, neuropathy and hyperalgesic priming." (PMID 29394316, 2018).
Tinnitus (22 papers, 2014 to 2025). Tinnitus is an auditory perception that can be described as the experience of sound, in the ear or in the head, in the absence of external acoustic stimulation. "BDNF Val66Met polymorphism can result in suffering with the associated worsening of tinnitus loudness perception." (PMID 40217670, 2025). "In summary, we found that in chronic tinnitus patients, higher tinnitus loudness is associated with higher hair-cortisol and lower hair-BDNF levels, whereas higher levels of tinnitus-related distress are additionally associated with lower hair-BDNF levels." (PMID 35121746, 2022). "This study investigates hair-cortisol and hair-BDNF in chronic tinnitus patients and their associations with tinnitus-related and psychological factors while adequately controlling for confounding influences by elastic net regression." (PMID 35121746, 2022). "For a better understanding of neurobiological changes in chronic tinnitus, further studies on the associations of neuroplasticity changes, especially of the hippocampus, with tinnitus-related distress and hair-BDNF levels are needed." (PMID 35121746, 2022). "Interesting in this context is that lower BDNF activation was previously associated with enhanced distress levels in tinnitus patients that suffered from BDNF Val66Met polymorphism." (PMID 35069123, 2021). "Prior work suggests that cochlear neuropathologic changes, such as loss of IHC synapses and changes in BDNF or c-Fos levels in the SG, trigger downregulation of Arc in central auditory pathways, which has been correlated with tinnitus." (PMID 33411811, 2021). "(iv)Increased susceptibility to a clinical manifestation of tinnitus linked to enhanced tinnitus-related distress, as observed in patients with brain-derived neurotrophic factor (BDNF) Val66 Met polymorphism." (PMID 34686939, 2021). "Deficits in BDNF driven GR phosphorylation and LTP retention should be considered in the context of enhanced tinnitus-related distress in patients suffering from the BDNF Val66Met polymorphism." (PMID 34686939, 2021). "Human serum contains BDNF at much higher concentrations (factor 200) than human plasma, and it was more linked to hyperacusis and tinnitus." (PMID 33383894, 2020). "There are, however, conflicting reports on the association between tinnitus and plasma or serum BDNF." (PMID 32747715, 2020). "PCR-based RFLP analysis in 240 German patients with Tinnitus Questionnaire (TQ)-scored subjective chronic primary tinnitus has been performed for the genes BDNF and GDNF, encoding brain and glial cell-derived neurotrophic factors, respectively." (PMID 28533738, 2017). "Although we observed no treatment effect for hair-BDNF, general associations of baseline tinnitus-related distress, tinnitus loudness, and hearing threshold with hair-BDNF levels at both measurements were found, extending our cross-sectional findings (baseline measurements) in the same sample." (PMID 35250657, 2022). "Whether our observed effects of tinnitus-related distress and traumatic experiences on hair-BDNF levels are influenced by the Val66Met polymorphism could be an interesting future research question." (PMID 35121746, 2022). "However, based on the observed association with tinnitus-related distress, we expect hair-BDNF levels to increase in parallel with treatment-induced reductions in tinnitus-related distress." (PMID 35250657, 2022). "Measurement of hair-BDNF may offer a new approach to clarify the long-term neuroendocrine changes in chronic tinnitus and associations of BDNF with tinnitus-related distress." (PMID 35121746, 2022). "Genetics has been little explored in the context of tinnitus, with a few potential genes screened, including associated cardiovascular genes, neurotropic factors of BDNF and GDNF, potassium recycling pathway genes, GABAB receptor subunits, and serotonin receptor/transporters." (PMID 36556140, 2022).
Tinnitus (continued). "Our results show that in chronic tinnitus patients, tinnitus loudness is associated with both increased hair-cortisol and decreased hair-BDNF levels, and tinnitus-related distress is associated with decreased hair-BDNF levels." (PMID 35121746, 2022). "Based on assumed long-term stress-related effects in chronic tinnitus patients, our hypotheses are that increased hair-cortisol levels and decreased hair-BDNF levels are associated with higher tinnitus-related distress." (PMID 35121746, 2022). "Here, for example, the absence of hereditary contributors to enhanced distress, which have been shown to increase susceptibility to tinnitus, including the BDNF Val 66 Met polymorphism, have to be regarded in the context of a possible contribution to tinnitus resilience and long-term habituation." (PMID 34686939, 2021). "Enhanced tinnitus-related distress, as observed in patient groups with BDNF Val66 Met polymorphism would be compatible with BDNF bridging glucocorticoid effects on brain networks through BDNF driven phosphorylation of glucocorticoid receptor." (PMID 34686939, 2021). "Previous observations that describe elevated intensity discrimination thresholds in tinnitus subjects with normal audiograms may be re-examined in the context of a loss of signal-to-noise ratio in those frequency bands in which the BDNF-dependent driving force is lost." (PMID 26476841, 2016). "BDNF is present in all processes as the top1 HDP, reflecting the well-known special role of BDNF in brain plasticity or as the driving force for inhibitory circuits, including for inhibitory circuits during tinnitus." (PMID 40076458, 2025). "The results of these alterations indicate that c-fos, EGR-1, and BDNF are probably involved in the regulation of neural excitability in response to cerebral venous congestion-related tinnitus." (PMID 38594782, 2024). "Conflicting studies revealed either lower or higher levels of plasma BDNF in baseline individuals with tinnitus when compared to non-tinnitus controls." (PMID 38079022, 2023). "Lastly, the investigated clinical sample was heterogeneous, and we observed a small predictive effect of constant vs. intermittent tinnitus on hair-BDNF levels." (PMID 35121746, 2022). "As expected, higher tinnitus-related distress was related to lower hair-BDNF, consistent with findings by34, where highly distressed tinnitus patients had lower serum BDNF levels than patients with mild distress." (PMID 35121746, 2022). "Implications include the potential use of hair-cortisol and hair-BDNF as biomarkers of tinnitus loudness or distress and the need for intensive future research into chronic stress-related HPA axis and neuroplasticity alterations in chronic tinnitus." (PMID 35121746, 2022). "Despite the absence of treatment-induced changes in hair-BDNF levels, our exploratory results tentatively suggest the possibility of a time-lagged effect of tinnitus-related distress (at baseline) affecting hair-BDNF levels (at follow-up)." (PMID 35250657, 2022). "Further studies are needed to investigate treatment-induced changes in hair-biomarkers in chronic tinnitus, especially hair-BDNF, to obtain a better understanding of stress-related effects in chronic tinnitus." (PMID 35250657, 2022). "This study was the first to analyze hair-cortisol and hair-BDNF levels in chronic tinnitus patients." (PMID 35121746, 2022). "Based on our results, we expect higher hair-cortisol and lower hair-BDNF levels in patients with loud and distressing chronic tinnitus than healthy controls, but this assumption remains to be tested." (PMID 35121746, 2022). "Louder tinnitus was related to lower hair-BDNF and higher hearing thresholds to higher hair-BDNF levels at baseline and follow-up." (PMID 35250657, 2022). "The relationship between tinnitus-related distress and hair-BDNF levels should be explored further to obtain a better understanding of stress-related effects in chronic tinnitus." (PMID 35250657, 2022).
Tinnitus (continued). "Overall, further research is needed for a better understanding of the relationship between tinnitus-related distress and hair-BDNF levels." (PMID 35250657, 2022). "The exploratory cross-lagged panel analysis (research question 4) tentatively suggests that the possibility of a time-lagged effect of tinnitus-related distress affecting hair-BDNF levels is more likely than the opposite effect." (PMID 35250657, 2022). "High tinnitus-related distress and traumatic experiences appear to have additional detrimental effects on BDNF expression, whereas hearing aid use and high physical health-related quality of life appear beneficial." (PMID 35121746, 2022). "In animal studies, it has been found that BDNF expression in the inner ear increases when tinnitus is induced." (PMID 34205595, 2021). "Here, BDNF signaling needs to be considered as a potential bridge linking bottom-up changes in tinnitus with an altered distress network." (PMID 34686939, 2021). "In another study, plasma BDNF levels in patients with tinnitus were higher than those in the control group, and decreased after TRT in patients with severe tinnitus." (PMID 34205595, 2021). "After treatment ceased animals were tested for tinnitus, underwent single-neuron recordings in inferior colliculus to assess hyperactivity and samples from cortex and inferior colliculus were taken for BDNF ELISA." (PMID 27905540, 2016). "Though no cure currently exists, repetitive transcranial magnetic stimulation (rTMS) has been shown to reduce tinnitus in some patients, possibly via induction of cortical plasticity involving brain derived neurotrophic factor (BDNF)." (PMID 27905540, 2016). "The ability of PBMT to stimulate BDNF may explain its effects on reducing harmful neuroplasticity in tinnitus, however further research is needed to confirm this." (PMID 38626075, 2024). "For hair-cortisol, no predictive influences were identified; for hair-BDNF, general associations with tinnitus-related distress, tinnitus loudness, and hearing threshold were found." (PMID 35250657, 2022). "This suggests hair-BDNF might be a useful biomarker to assess the clinical efficacy of treatments targeting tinnitus-related distress." (PMID 35121746, 2022). "In this longitudinal study, hair-cortisol and hair-BDNF levels, self-reported tinnitus-related distress (Tinnitus Questionnaire; TQ), and perceived stress (Perceived Stress Questionnaire; PSQ-20) were assessed before and 3 months after 5 days of treatment in N = 80 chronic tinnitus patients." (PMID 35250657, 2022). "Chronic tinnitus might be related to long-term changes in cortisol and BDNF expression, the strength of which may be moderated by perceived tinnitus loudness." (PMID 35121746, 2022). "This study explores whether stress-related biomarkers cortisol and brain-derived neurotrophic factor (BDNF) measured in hair samples of chronic tinnitus patients change after compact multimodal tinnitus-specific cognitive behavioral therapy." (PMID 35250657, 2022). "In addition, the exploratory analysis provided tentative and limited evidence of a time-lagged effect of tinnitus-related distress (at baseline) on hair-BDNF levels (at follow-up)." (PMID 35250657, 2022). "The mixed results of previous studies on BDNF levels in tinnitus patients might be related to situational influences on BDNF measurement in blood." (PMID 35121746, 2022). "While this trend needs to be tested in larger-scale studies, it may further indicate that more substantial treatment-induced changes in tinnitus-related distress may be necessary to elicit measurable changes in hair-BDNF levels." (PMID 35250657, 2022). "However, the combination of BDNF and GDNF gene polymorphisms was more associated with the severity of tinnitus in women than in men." (PMID 34205595, 2021). "Another study reported that the plasma BDNF level was low in patients with tinnitus, but the BDNF gene polymorphism was not different from that of the control group." (PMID 34205595, 2021).